PMS2 (PMS1 homolog 2, mismatch repair system component)
Diseases named in the same sentence as PMS2 in open-access papers (continued):
Sharing a sentence is not in itself a finding about the gene and the disease.
colon carcinoma (50 papers, 2010 to 2025). "Among MMR-associated genes, MSH6 and PMS2 were significantly more frequently mutated in CDX2-suppressed colon cancers, and the same was true for mutations in the proofreading polymerases POLE and POLD1 genes." (PMID 39452477, 2024). "The proband underwent genetic testing with a colon cancer gene panel, which consisted of genes from both syndromes; it resulted in an unexpectedly positive deleterious mutation in PMS2." (PMID 29225998, 2016). "A targeted gene sequencing test (next-generation sequencing (NGS)) for 88 genes related to colon cancer found mutations in two different genes: the PMS2 (p.Arg20Gln) and the WRN (p.Leu628Val) genes (for more information)." (PMID 25018888, 2014). "Our study thus focused on patients ≥50 years of age, 23% of whom had MMR deficient colon cancers with loss of MLH1/PMS2 in 86% of the cases." (PMID 24341444, 2013). "This pattern of expression of Pms2 is typical for crypts within the colonic epithelium of patients at low risk for colon cancer." (PMID 22494821, 2012). "We next consider the extent of the field defects that are deficient in Pms2 and Ercc1 in colon segments that were resected, due either to the presence of colon cancer or due to large tubulovillous adenomas." (PMID 22494821, 2012). "The microRNA, miR-155, is over-expressed in colon tumors as well, and also down-regulates Mlh1, which in turn would cause reduced expression of Pms2." (PMID 22494821, 2012). "Our observations indicate that MSI analysis may be used to identify PMS2 mutation carriers among patients with extra-colonic as well as colonic cancers." (PMID 24790682, 2014). "We were also interested in whether deficiencies in protein expression of Pms2, Ercc1, Xpf or Ku86 could be biomarkers of colon cancer risk within biopsies taken during colonoscopies." (PMID 22494821, 2012). "This suggests that colon cancers tend to arise in field defects that are deficient in DNA repair and that deficiencies in protein expression of Pms2, Ercc1 and Xpf are frequent early, and often coordinated, steps in progression to colon cancer, as well as further progression within cancers." (PMID 22494821, 2012). "This instability would be expected to enhance progression to colon cancer by causing a mutator phenotype, and could also account for the presence of the cells doubly deficient in Pms2 and Ercc1 (or Xpf) we observed in field defects associated with colon cancer." (PMID 22494821, 2012). "P-012 developed a colon cancer at 55 years and sebaceous adenoma at 61 years of age, with both tumours demonstrating MLH1/PMS2-deficiency and positivity for MLH1 hypermethylation." (PMID 40208414, 2025). "One female patient was very young at diagnosis (25 years, left colon cancer), with MSI high, assessed using IHC (loss of expression of MLH1 and PMS2) and PCR." (PMID 38731914, 2024). "The IHC staining of the colon biopsy showed deficiency for PMS2 (Subject 1) and MSH6 (Subject 2) proteins, with intact status for other MMR proteins, a pattern consistent with LS-associated colon cancer with germline involvement as a first hit." (PMID 36091175, 2022).
colon carcinoma (continued). "The only exception was for PMS2 gene in colon tumors, where patients with the pTNM stage I + II had significantly lower expression levels than those with pTNM III + IV (−1.13, P = 0.01; data not shown)." (PMID 24484585, 2014). "Substantially reduced protein expression of Pms2, Ercc1 and Xpf occurred in field defects of up to 10 cm longitudinally distant from colon cancers or TVAs and within colon cancers." (PMID 22494821, 2012). "We studied 46 MSI-H colon tumors showing loss of MLH1 expression and its heterodimer PMS2 and methylation of the MLH1 promoter." (PMID 20444249, 2010). "Somatic mutations in DNA repair genes are infrequent in sporadic cancers, and no Pms2 or Xpf mutations were found in Pms2 and Xpf gene sequences of 11 colon cancers." (PMID 22494821, 2012). "There were also 32 tissue samples obtained at 1-10 cm from colon cancers (removed during resection) that were cut as triplicates and immunostained for Pms2, Ercc1 and Xpf, as well as 38 additional tissue samples obtained at 1-10 cm from colon cancers that were immunostained for Ku86." (PMID 22494821, 2012). "This is particularly relevant for the PMS2 gene since, based on data from first degree relatives in the Colon Cancer Family Registry, the frequency of PMS2 PV carriers in the general population is 1 in 714 and they may not present as LS due to the low penetrance of PMS2 PV in the heterozygous state." (PMID 39420201, 2024). "From the eight members of family D, four brothers were diagnosed with colon cancer, all of whom underwent partial colectomy, including the index case (PIII.3) that was diagnosed at the age of 46 with tumor presenting loss of MLH1 and PMS2 proteins expression and MSI-H." (PMID 36454741, 2022). "Due to the important role of ROS in cancer and the indication that Pms2 and Ercc1 are specific targets of ROS, we directed our attention to evaluating whether Pms2 and Ercc1 (and Xpf, the pairing partner of Ercc1) were systematically reduced in progression to colon cancer." (PMID 22494821, 2012). "The levels of expression of DNA repair proteins Pms2, Ercc1 and Xpf were evaluated by immunohistochemistry (IHC) in sequential tissue sections from individuals who never had a colonic neoplasm, and thus are at low risk of colon cancer." (PMID 22494821, 2012). "In the reported DL results, a positive fraction of 5 % was used as threshold to assess the presence of PMS2 and MSH6 in colon cancer." (PMID 39040241, 2024). "A gene mutation of MLH1was suspected in this family line, because all of the colon cancers demonstrated complete defects of MLH1 and PMS2." (PMID 32611331, 2020). "This case supports a plausible mechanism, proposed by a previous literature, for the reduced expression of MSH6 in a somatic mutation manner, which might preferentially happen in colon cancer rather than in stomach carcinoma in MLH1/PMS2-deficient type of Turcot’s syndrome type 1." (PMID 32611331, 2020). "In addition no Pms2 or Xpf mutations were found in Pms2 and Xpf gene sequences of 11 colon cancers." (PMID 22494821, 2012).
colon carcinoma (continued). "Immunohistochemistry of participants A’s colon cancer biopsy demonstrated loss of protein expression of MLH1 and PMS2, indicative of MLH1 loss of function, and no BRAF V600 mutation was found in tumour DNA." (PMID 34711244, 2021). "Transverse colon cancer, IHC = MLH1/PMS2 absent (MLH1 promoter methylation analysis showed methylation)." (PMID 33193653, 2020).
prostate carcinoma (29 papers, 2014 to 2024). A carcinoma that arises from epithelial cells of the prostate gland. "In prostate cancer, overexpression of MSH6, MLH1 and PMS2 proteins associates with poor disease outcome and genetic instability in a cohort of 11,152 prostate cancer patients." (PMID 36482191, 2023). "The VUS detected in the PMS2 gene (c.184G>A; p.Gly62Ser) was identified in a male patient (family 21) who developed prostate cancer, CRC, and biliary tract cancer between 65 and 66 years of age." (PMID 37894428, 2023). "For likely pathogenic mutations, FANCM and FH ranked top for kidney cancer, RAD51C ranked top for bladder cancer, and ATM and PMS2 ranked top for prostate cancer." (PMID 36451132, 2022). "In prostate, the functional role of this gene has never been reported and in this study, our aim was to investigate the effect of PMS2 on growth properties of prostate cancer (PCa) cells." (PMID 26036629, 2015). "recognized PMS2 elevation as a prognostic marker in pre-neoplastic and prostate cancer lesions." (PMID 35865481, 2022). "However, overexpression of PMS2 was previously reported to confer genetic instability and DNA-damage tolerance in prostate cancer." (PMID 29371938, 2017). "A study using a subcutaneous xenograft mouse model with prostate cancer cells lacking PMS2 protein (DU145) demonstrated that PMS2 played a role as a tumor suppressor by increasing apoptosis upon its introduction." (PMID 33247565, 2021).
Familial adenomatous polyposis (26 papers, 2009 to 2025). Familial adenomatous polyposis (FAP) is characterized by the development of hundreds to thousands of adenomas in the rectum and colon during the second decade of life.
mismatch repair deficiency (26 papers, 2016 to 2025). "Deficiency in PMS2/MLH1 genes was the most common cause of mismatch repair deficiency with a frequency of 70.8% (n = 12)." (PMID 40018347, 2025). "Although no second hit was found, these data orient towards the probable existence of mismatch repair deficiency, supporting a causal role for the PMS2 variant and the presence of a second hit of a different type (e.g., an epigenetic event)." (PMID 32295625, 2020). "Weaknesses of this study include inclusion of only one tumor from a PMS2 pathogenic variant carrier, who had constitutional mismatch repair deficiency." (PMID 31998307, 2019). "A homozygous pathogenic variant in PMS2 (p.S459X) diagnostic of congenital mismatch repair deficiency was identified in one patient with T-cell lymphoblastic lymphoma and consanguineous parentage." (PMID 28007021, 2016). "Given that the HEC1A cell line has a baseline mismatch repair deficiency (PMS2 mutation) and high mutation burden, we directed and interpreted our analysis on the unshared mutations between the two comparison groups to be representative of newly gained mutations following lentiviral transduction." (PMID 38067377, 2023). "With respect to mismatch repair deficiency, we observed potentially pathogenic somatic variants in CRC_4 (MLH1 p.S404Y), CRC_6 (MLH1 p.R497G_fs & PMS2 p.T680M), and CRC_2 (PMS2 p.E745K)." (PMID 38504345, 2024).
mismatch repair deficiency (continued). "Furthermore, the large majority of analyzed patients showed MMR deficiency for MLH1 and PMS2." (PMID 32576892, 2020).